CNPY4 (canopy FGF signaling regulator 4)
Description:
Plays a role in the regulation of the cell surface expression of TLR4.
Synonyms: MGC40499; PRAT4B
Tractability: Antibody: UniProt places it where antibodies can reach, with high confidence; UniProt predicts a signal peptide or a membrane-spanning region; its Gene Ontology location is reachable by antibodies, with medium confidence. PROTAC: its protein half-life has been measured.
Gene: Protein-coding gene on chromosome 7 (100,119,634 to 100,125,508, forward strand). Ensembl gene ENSG00000166997.
Subcellular location: Secreted
Subcellular location (Human Protein Atlas): Vesicles
Gene Ontology:
Molecular function: protein binding; signaling receptor binding
Biological process: positive regulation of protein localization to plasma membrane
Cellular component: extracellular region
Genetic constraint (gnomAD): Loss-of-function variants: 30 observed, 30.6 expected, observed/expected ratio (o/e) 0.98, 90% interval 0.73 to 1.33. The upper end of that interval is the gene's LOEUF score, 1.33, which puts it in group 5 of 6, group 1 being the genes least tolerant of losing a copy. Missense variants: 321 observed, 318.11 expected, observed/expected ratio (o/e) 1.01, 90% interval 0.92 to 1.11. Synonymous variants: 109 observed, 116.6 expected, observed/expected ratio (o/e) 0.93, 90% interval 0.8 to 1.1.
Homologues: Orthologues: chimpanzee CNPY4 (99% identical), macaque CNPY4 (95% identical), pig CNPY4 (85% identical), rabbit CNPY4 (84% identical), rat Cnpy4 (83% identical), guinea pig CNPY4 (83% identical), mouse Cnpy4 (82% identical), zebrafish cnpy4 (50% identical), Drosophila melanogaster CNPYb (41% identical), Caenorhabditis elegans C11H1.7 (24% identical). Paralogues in human: CNPY3 (43% identical).
Diseases named in the same sentence as CNPY4 in open-access papers:
CNPY4 is named in the same sentence as 9 diseases in open-access papers, as found by Europe PMC text mining. Sharing a sentence is not in itself a finding about the gene and the disease. The quoted sentences say what the papers report.
autoimmune thyroid disease (1 paper, 2022). Inflammatory disease of the thyroid gland due to autoimmune responses leading to lymphocytic infiltration of the gland. "The results showed that immunoregulatory interactions between lymphoid and nonlymphoid cells, the internal immune network for IgA production, autoimmune thyroid disease, primary immunodeficiencies, and cancer immunotherapy by PD-1 blockade were differentially enriched due to CNPY4 overexpression." (PMID 35984129, 2022).
glioblastoma (1 paper, 2022). The most malignant astrocytic tumor (WHO grade IV). "CNPY4 expression was correlated with the infiltration level of dendritic cells in glioblastoma." (PMID 35984129, 2022).
glioma (1 paper, 2022). A benign or malignant brain and spinal cord tumor that arises from glial cells (astrocytes, oligodendrocytes, ependymal cells). "First, we used the GEPIA online database to reveal that CNPY4 expression was associated with the survival of glioma patients." (PMID 35984129, 2022). "High CNPY4 expression is a biomarker of glioma prognosis and is associated with the immune invasion of glioma." (PMID 35984129, 2022). "Furthermore, additional studies are needed to analyze the mechanisms underlying the pathophysiological role of CNPY4 in gliomas." (PMID 35984129, 2022). "In addition, we revealed that CNPY4 expression was associated with the prognosis of glioma, and the downregulation of CNPY4 expression was an independent and satisfactory prognostic factor." (PMID 35984129, 2022). "Using GSEA, we identified immune-related signaling pathways involved in glioma with high and low expression of CNPY4." (PMID 35984129, 2022). "Based on gene expression profile interaction analysis (GEPIA), we studied the survival model of CNPY4 and evaluated its effect on patients with glioma." (PMID 35984129, 2022). "More importantly, multivariate regression analysis suggested that CNPY4 expression was an independent prognostic factor in glioma patients." (PMID 35984129, 2022). "Based on these findings and results from previous studies, the relationship between CNPY4 expression and glioma immune infiltration can be studied." (PMID 35984129, 2022). "The relationship between CNPY4 and immune infiltration in glioma was studied using GEPIA and CIBERSORT online tools." (PMID 35984129, 2022). "Here, we aimed to demonstrate the role of the CNPY4 gene as a potential biomarker in immune infiltration in gliomas." (PMID 35984129, 2022). "CIBERSORT revealed that CNPY4 expression was positively correlated with the proportion of dendritic cells in gliomas." (PMID 35984129, 2022). "Therefore, in the present study, we investigated the potential role of CNPY4 in glioma and analyzed its expression in human glioma patients using TCGA and RNA-seq databases." (PMID 35984129, 2022). "In the present study, we demonstrated the relationship between CNPY4 and gliomas." (PMID 35984129, 2022). "Finally, TIMER was used to analyze the expression and immune infiltration of CNPY4 in glioma to study the cumulative survival rate." (PMID 35984129, 2022). "Furthermore, we showed the important effect of CNPY4 on dendritic cell immune infiltration in glioma." (PMID 35984129, 2022). "The findings of this study revealed that CNPY4 is a key gene in gliomas that might serve as a prognostic biomarker, and CNPY4 expression may be used to investigate immune infiltration in glioma patients." (PMID 35984129, 2022). "Moreover, we found that different degrees of immune infiltration and immune marker sets were related to CNPY4 expression in gliomas." (PMID 35984129, 2022). "CNPY4 mRNA expression was correlated with the tumor in glioma patients." (PMID 35984129, 2022). "Therefore, in this study, we explored the relationship between CNPY4 gene expression and glioma using bioinformatics." (PMID 35984129, 2022). "CNPY4 may be an immune prognostic index and therapeutic target of glioma." (PMID 35984129, 2022). "In contrast, in low-grade gliomas, the infiltration level of B cells, dendritic cells, macrophages, neutrophils, and CD4+ T cells was significantly correlated with CNPY4 expression." (PMID 35984129, 2022).
Insulin resistance (1 paper, 2025). Increased resistance towards insulin, that is, diminished effectiveness of insulin in reducing blood glucose levels. "Taken together, these results suggest that FAM20C-mediated phosphorylation of CNPY4 at Ser64 promotes proinflammatory gene expression and contributes to AT insulin resistance in obesity." (PMID 41148235, 2025). "Future in vivo studies are needed to define the role of CNPY4 in insulin resistance and adipose inflammation." (PMID 41148235, 2025).
Obesity (1 paper, 2025). Accumulation of substantial excess body fat. "Notably, mouse Cnpy4 encodes 3 isoforms, and variant-specific qPCR revealed a distinct expression pattern in VIS WAT during obesity." (PMID 41148235, 2025). "Furthermore, we report an obesity-associated, isoform-specific change in Cnpy4 expression in VIS WAT, with isoform 2 being selectively induced, suggesting that posttranscriptional regulation of Cnpy4 may further shape inflammatory and metabolic outputs in obesity." (PMID 41148235, 2025).
Tumor (1 paper, 2022). "Next, we analyzed TCGA data using R software (v3.5.3), revealing that CNPY4 expression was associated with tumor grade, age, IDH status, and 1p/19q codeletion." (PMID 35984129, 2022). "Univariate logistic regression analysis showed that increased CNPY4 expression was associated with tumor age, grade, IDH status, and 1p/19q codeletion." (PMID 35984129, 2022). "In summary, CNPY4 expression was considered related to the neoplasm grade with the increase in tumor size." (PMID 35984129, 2022). "Using multivariate analysis, age, neoplasm grade, and CNPY4 expression were confirmed to be independent prognostic factors." (PMID 35984129, 2022). "Analyzing the genes in different immune cells and CNPY4 expression, we clarified that CNPY4 markedly influences the regulation of the tumor immune microenvironment." (PMID 35984129, 2022). "First, due to the limitations of these open databases, some important clinical parameters, such as tumor resection degree, tumor measurement and area, and preoperative status, may affect the high expression of CNPY4." (PMID 35984129, 2022). "We believe that CNPY4 can eventually be used as an effective tumor biomarker." (PMID 35984129, 2022).
CNPY4 also shares sentences with these, for which no sentence is quoted: cancer (2 papers); gout (1); primary immunodeficiencies (1).